BDNF (brain derived neurotrophic factor)
Diseases named in the same sentence as BDNF in open-access papers (continued):
Sharing a sentence is not in itself a finding about the gene and the disease.
depression (continued). "Recently BDNF has emerged as a major factor in the pathophysiology of depression: BDNF mRNA is increased in the rat brain following chronic anti-depressant or electro-convulsive shock treatment." (PMID 15876359, 2005). "Specifically, we observed that CUMS-induced depression models exhibited profound molecular dysregulation characterized by significant BDNF suppression, pathological EGFR overexpression, ERK2 downregulation, pro-inflammatory JUN elevation, RAF1 repression, and chronic stress-driven TNF upregulation." (PMID 41438694, 2026). "Brain-derived neurotrophic factor (BDNF), a key regulator of synaptic plasticity and neurogenesis, has also been examined, with lower circulating levels associated with worse cognitive outcomes and depression in certain cancer cohorts." (PMID 41572047, 2026). "The profound BDNF suppression in CUMS models represents a hallmark of depression-related synaptic dysfunction, consistent with the neurotrophic hypothesis of depression." (PMID 41438694, 2026). "Curcumin's dose-dependent restoration of BDNF expression directly links to the observed behavioral improvements, particularly in the sucrose preference test, which measures anhedonia—a core symptom of depression." (PMID 41438694, 2026). "A bibliometric analysis conducted between 2004 and 2023 on neuroinflammation in depression highlighted the NLRP3 inflammasome, microglia, tumor necrosis factor‐alpha (TNF‐α), and brain‐derived neurotrophic factor (BDNF) as central components in the underlying pathogenic mechanisms." (PMID 41479745, 2026). "Furthermore, the authors demonstrated that incorporating Crocus sativus (saffron) into the diet can boost hippocampal BDNF levels and alleviate depression symptoms." (PMID 41465304, 2025). "A significant gap remains in understanding how exercise-induced BDNF changes might help alleviate specific symptoms, including fatigue, pain, sleep disturbances, and depression." (PMID 40002745, 2025). "We speculated that there must be BDNF expression changes in the intersection of the pathological changes within PD and depression." (PMID 39609371, 2025). "Recent meta-analyses and systematic reviews confirm that BDNF levels are significantly lower, both in the blood and in the CNS, in patients with depression compared to controls; moreover, lower peripheral BDNF levels have been associated with more severe symptoms." (PMID 41463298, 2025). "Individuals with depression who have experienced multiple recurrences may exhibit lower concentrations of BDNF and 5-HT in the serum compared to those with single or fewer recurrences." (PMID 41477617, 2025). "However, transcription of BDNF gene decreases in the brain tissue of patients with severe depression, which correlates with reduced cerebral blood flow (CBF) particularly in the anterior cingulate and prefrontal cortex." (PMID 41327464, 2025). "The discrepancies in BDNF levels observed in studies involving depression and ECT may arise due to several factors." (PMID 40565369, 2025). "Studies have demonstrated that Brain-derived Neurotrophic Factor (BDNF) signal transduction is essential for synaptic plasticity in depression, and that BDNF downregulation may have neurotoxic consequences." (PMID 40951640, 2025). "In a study of coronary heart disease (CHD) patients comorbid with depression, the serum levels of irisin, adropin, preptin, and brain-derived neurotrophic factor (BDNF) were significantly reduced in both CHD patients with depression and those without depression." (PMID 40431406, 2025). "The neurotrophic hypothesis of depression posits that reduced levels of BDNF significantly contribute to the pathophysiology of major depressive disorder." (PMID 40004867, 2025). "To investigate whether NAc-DBS relieves the hippocampal injuries and mitigates depression-like behavior in mice by enhancing the BDNF protein and activating the mTOR pathway, we used Western blots and RT-qPCR to detect changes in mTOR pathway." (PMID 41234534, 2025).
depression (continued). "The level of BDNF is closely related to depression, cognitive function, and SQ." (PMID 40821647, 2025). "Translationally, BDNF genotype has been linked to tDCS efficacy in stroke-related aphasia recovery, though not in depression." (PMID 41440017, 2025). "Research has shown that dietary patterns enhancing BDNF levels may improve depression outcomes, suggesting a potential link between diet and mental health." (PMID 40224525, 2025). "Clinical studies indicate that variations in blood BDNF levels may serve as an early marker of depression in stroke patients." (PMID 40458804, 2025). "Based on numerous studies indicating that decreased serum or plasma levels of BDNF in depressed patients recovered to normal levels after antidepressant treatment, it was proposed that circulating BDNF levels may be a biomarker of depression." (PMID 40332094, 2025). "Reduced SCFA levels are commonly reported in depression and anxiety models; oral sodium propionate can ameliorate depressive-like behaviors by increasing central histone H3 acetylation levels and activating BDNF expression, among other mechanisms." (PMID 41017972, 2025). "Clinical studies further confirm the connection between BDNF levels and depression." (PMID 39935532, 2025). "Multiple aspects of these processes are implicated in the development of anxiety and depression in CCH, including aberrant GABA and glutamate signaling, reduced BDNF, impaired synaptic potentiation, changes in synaptophysin, serotonin, and HCN1, as well as reduced dopamine and KCNQ3 activity." (PMID 39851502, 2025). "According to the neurotrophic hypothesis of depression, low levels of BDNF could reduce neurogenesis and lead neurons to cell death." (PMID 40426852, 2025). "Genome‐wide studies have identified candidate genes and pathways linked to PPD, focusing on those associated with major depressive disorder like serotonin transporter, Tryptophan hydroxylase 2 (TPH2), Catechol‐O‐Methyltransferase, Monoamine oxidase, and Brain‐derived neurotrophic factor (BDNF)." (PMID 40041772, 2025). "In depression and other psychiatric disorders, studies show alterations in BDNF activity, postulating it as the central element of the neurotrophic hypothesis." (PMID 41373743, 2025). "SSA therapy significantly enhanced the expression of p-CREB and BDNF, decreased the expression of Bax and Caspase-3, elevated the expression of Bcl-2, and inhibited the death of hippocampal neurons, thereby ameliorating depression-like behavior in PSD rats." (PMID 40458804, 2025). "The investigation of the correlation between BDNF levels and the severity of depression in patients with major depressive disorder reveals a negative association between low BDNF levels and the intensity of depression symptoms." (PMID 40822487, 2025). "Furthermore, Kaempferol-3-O-sophoroside not only improves depression-like behavior in mice but also promotes BDNF production in the hippocampus and induces autophagy to reduce NLRP3-mediated neuroinflammation." (PMID 40936908, 2025). "p-coumaric acid protects the chronic restraint stress-induced memory deficit and depression-like behavior by upregulating protein kinase A, phosphorylated cAMP response element binding protein (pCREB), and brain-derived neurotrophic factor (BDNF) expression in chronic restraint stress mice." (PMID 41471791, 2025). "In conclusion, CBS/H2S may ameliorate anxiety and depression-like behaviors by activating the CREB/BDNF signaling pathway in the hippocampus of mice exposed to IFS." (PMID 40551819, 2025). "In addition, microglia activation can reduce BDNF secretion, inhibiting neurodevelopment, growth, maturation, impairing synaptic plasticity, and ultimately disrupting neurons to induce depression." (PMID 41278468, 2025). "Conversely, among men with depression (n = 293), both severe [−5.12 g/mL (−9.26, −0.99)] and interfering [−4.95 g/mL (−8.29, −1.61)] pain were linked to lower BDNF, a trend absent in depressed women." (PMID 40222813, 2025).
depression (continued). "Decreased expression of BDNF is assumed to have roles in the pathogenesis of depression." (PMID 39985579, 2025). "Furthermore, emerging evidence identifies the combined biomarkers of elevated serum IL-6 levels and reduced BDNF concentrations as reliable predictors of depression severity, laying the foundation for multidimensional biomarker assessment systems." (PMID 41200224, 2025). "Additionally, BDNF Met/Met increases the risk of thrombotic events in patients with CVD and depression." (PMID 41301929, 2025). "Moreover, Lactobacillus paracasei PS23 was shown to enhance the brain-derived neurotrophic factor (BDNF), which plays an important role in neuronal survival in a chronic corticosterone-induced depression mice model." (PMID 40871217, 2025). "Epigenetic changes have been well-established in BDNF, COMT, FKBP5, NR3C1, SLC6A4, and DRD2, genes associated with psychiatric disorders, including schizophrenia, major depressive disorder (MDD), bipolar disorder (BP), post-traumatic stress disorder (PTSD), and autism spectrum disorder (ASD)." (PMID 41234420, 2025). "In addition, a previous report suggested that excessive autophagy reduces BDNF expression in neurons and disrupts hippocampal neurogenesis in corticosterone‐induced depression model mice." (PMID 39715728, 2025). "Although the Val66Met polymorphism in the BDNF gene does not inhibit BDNF production, its functional implications, particularly in depression, remain under investigation." (PMID 40003622, 2025). "Depressive episodes induce changes in various depression-related mechanisms, such as disruptions in endocrine balance leading to decreased serotonin levels and alterations in neurotrophic factor levels, such as reduced BDNF concentrations in the serum." (PMID 41477617, 2025). "This in turn leads to beneficial effects, including reduced LDL cholesterol and insulin resistance (HOMA‐IR), increased brain‐derived neurotrophic factor (BDNF) levels, and decreased depression and anxiety, as well as decreased markers of inflammation (CRP, and calprotectin) and cancer (CEA)." (PMID 41142011, 2025). "This additional step helped us to pinpoint differences within a more homogeneous group of CP sufferers, thereby refining our understanding of how pain severity and interference might differentially affect BDNF levels depending on sex and depression status." (PMID 40222813, 2025). "Additionally, DHM alleviates depression/anxiety and alcohol-related disorders by restoring GABAergic transmission and BDNF/TrkB signaling and improves neuropathic pain via microglial polarization." (PMID 40740995, 2025). "Cytokines such as PGC-1α, NLRP3, and BDNF can influence mitochondrial energy metabolism by regulating mitochondrial biogenesis, immune inflammation, and neuroplasticity, thereby mediating the occurrence and progression of depression." (PMID 40699781, 2025). "At present, there are many hypotheses about the pathogenesis of depression, including the monoamine hypothesis, brain‐derived neurotrophic factor (BDNF) hypothesis, hypothalamic–pituitary–adrenal (HPA) axis hypothesis, and neuroinflammation hypothesis." (PMID 40913332, 2025). "BDNF is a neurotrophin that has been involved in the pathophysiology of depression." (PMID 41373743, 2025). "A previous study found that Res could alleviate rat depression-like behaviors through the elevation of brain-derived neurotrophic factor (BDNF)." (PMID 40002382, 2025). "Hippocampal BDNF downregulation is involved in the pathophysiology of depression." (PMID 40361157, 2025). "Lowered BDNF levels in individuals with depression may disrupt the normal functioning of neural connections and the growth of new neurons, resulting in decreased drive, enjoyment, and cognitive abilities." (PMID 40821647, 2025). "In addition, an extremely interesting animal study reported that a serotonin reuptake inhibitor, which is used for depression, increased the BDNF expression in the mouse brain." (PMID 39941545, 2025).
depression (continued). "Studies have examined the effect of drugs and herbs on depression by examining BDNF levels." (PMID 39972664, 2025). "In addition, mitochondrial transplantation significantly increased BDNF expression in mouse models of depression and TBI." (PMID 40502813, 2025). "In recent years, the role of BDNF in the development of depression has aroused extensive attention." (PMID 40821018, 2025). "Escin, a natural triterpenoid saponin from Aesculus chinensis (Suoluozi), alleviates CUMS-induced depression-like behaviors by modulating both the BDNF/TrkB/CREB and Toll-like receptor 4 (TLR4)/Myeloid differentiation factor 88 (MyD88)/NF-κB signaling pathways." (PMID 40936908, 2025). "Thus, the interplay between LBP and depression involves complex mechanisms, including the regulation of neurogenesis by BDNF." (PMID 41194467, 2025). "Brain-derived neurotrophic factor (BDNF) has emerged as a critical mediator of synaptic plasticity, adult neurogenesis, and neural adaptation processes that are fundamentally compromised in depression and mood disorders." (PMID 41149840, 2025). "Numerous studies have confirmed that BDNF is one of the important biomarkers of depression." (PMID 40969945, 2025). "In a recent meta-analysis, BDNF levels were found to be decreased in conditions such as bipolar disorder, major depressive disorder, obsessive-compulsive disorder, Parkinson’s disease, and schizophrenia compared to controls, while BDNF was increased in post-traumatic stress disorder." (PMID 40710529, 2025). "Furthermore, BDNF levels normalize after remission from psychiatric disease, particularly in depression but also potentially in other psychiatric diseases, such as eating disorders." (PMID 39613915, 2025). "Notably, activation of the PERK-eIF2α pathway in the hippocampus is associated with decreased brain-derived neurotrophic factor (BDNF) levels and depression-like behavior." (PMID 41473415, 2025). "This suggests that therapies aimed at increasing BDNF levels could be beneficial for treating depression." (PMID 40003622, 2025). "In conclusion, BDNF is a key neurotrophic factor in depression treatment, but its role in mediating clinical improvements through exercise remains unclear." (PMID 40665827, 2025). "A recent study proposed the brain-derived neurotrophic factor (BDNF) hypothesis, which demonstrates that depression is the consequence of attenuated neurogenesis and diminished neuroplasticity, with sequelae attributed to reduced levels of BDNF." (PMID 39936956, 2025). "Long-term stress might increase the levels of proBDNF, which can alter the BDNF signaling pathway and make depression worse by triggering the inflammatory reactions in the immune cells." (PMID 41465304, 2025). "Previous studies have shown that patients with depression have hippocampal atrophy (e.g., decreased neurogenesis), and reduced BDNF levels may be one of the reasons for the decreased neurogenesis." (PMID 40821018, 2025). "Chronic exposure to glucocorticoids has been shown to reduce the levels of brain‐derived neurotrophic factor (BDNF) and its receptor, tyrosine kinase receptor B (TrkB), in brain structures involved in depression and the regulation of cognitive and emotional processes." (PMID 41194467, 2025). "Importantly, BDNF levels in ADEVs were more stable than in plasma, suggesting that ADEVs are more suitable for biomarkers than plasma in depression." (PMID 40005159, 2025). "It has been reported that VNS can alleviate anxiety and depression by increasing BDNF levels." (PMID 40183201, 2025). "Conversely, pro-BDNF levels are elevated in depression but decline with treatment." (PMID 40428308, 2025). "Furthermore, one study related to depression has demonstrated the critical role of BDNF in the survival, growth, and maintenance of neurons in key brain circuits involved in mood and cognitive functions." (PMID 39609371, 2025).
depression (continued). "Notably, intraoperative ketamine application improved postoperative depression scores and elevated serum BDNF levels in patients undergoing elective orthopaedic surgery." (PMID 40223927, 2025). "We assessed changes in depression severity, cognitive function, and serum levels of 5-HT and BDNF." (PMID 41477617, 2025). "Specifically, our findings add to the body of evidence suggesting that the Val66Met polymorphism may influence neuropsychiatric outcomes, such as depression, by modulating BDNF availability and function." (PMID 40003622, 2025). "Additionally, tea polyphenols regulate microglia polarization (M1/M2) and enhance BDNF expression in the hippocampus, thereby alleviating depression-like symptoms in rats with type 2 diabetes." (PMID 39861389, 2025). "BDNF, which is crucial for neuronal survival and plasticity, is linked to mood disorders and suicide risk, while DRD2, involved in dopamine signaling, affects mood regulation and susceptibility to depression and suicidal tendencies." (PMID 39940809, 2025). "As well, metformin alleviates stress-induced depression in mice by enhancing BDNF signaling." (PMID 40380033, 2025). "Variability in BDNF responses has also been observed in pharmacological studies investigating its potential as a mechanistic biomarker for symptom improvement, particularly in depression." (PMID 40002745, 2025). "BDNF has been proven to play a critical role in the molecular mechanisms of depression." (PMID 41312464, 2025). "However, some different symptoms between depression and schizophrenia exist; a more detailed analysis of the contribution of the BDNF/TrkB system and its signaling pathway, using in vivo and in vitro models, is required." (PMID 40005159, 2025). "Although BDNF might act as a promising genetic marker for treatment response to CBT intervention in depression has been discussed, BDNF levels post-CBT treatment remain controversial." (PMID 41169487, 2025). "BDNF, as a brain-derived neurotrophic factor, was closely related to anxiety and depression." (PMID 40995228, 2025). "Kir4.1 may influence the pathogenesis of depression through multiple mechanisms, such as modulating [K+]o and glutamate concentration, as well as regulating BDNF secretion." (PMID 40001468, 2025). "There is a strong correlation between cortisol signaling and depression, and it has been shown that chronic glucocorticoid exposure leads to a decrease in the levels of BDNF mRNA and its proteins, as well as a decrease in the expression of its receptors, which can severely affect neuronal function." (PMID 40497971, 2025). "Wang and colleagues demonstrated that rTMS enhanced BDNF expression through ERK2 signaling in a rat depression model and found parallel increases in BDNF/NMDAR expression in both rat brain slices and human lymphocytes, suggesting conserved mechanisms across species." (PMID 41440017, 2025). "The mechanisms by which probiotics alleviate depression may involve the inhibition of inflammatory responses, the reduction of cortisol levels, and the enhancement of brain-derived neurotrophic factor (BDNF) expression." (PMID 40740336, 2025). "Furthermore, sex‐specific associations between CP and BDNF in older populations remain largely unexplored, and the impact of coexisting CP and depression on BDNF is rarely considered." (PMID 40222813, 2025). "The study revealed that NAc-DBS could attenuate depression-like behaviors, restore high gamma oscillation power and enhance synaptic spine density, potentially by increasing BDNF protein expression level and activating AKT/mTOR signaling pathway." (PMID 41234534, 2025). "The results regarding BDNF may appear contradictory to earlier findings (i.e., significant differences between aerobic exercise, rTMS, and the control group in influencing depression symptoms and cognitive function)." (PMID 41477617, 2025). "In clinical settings, boosting BDNF is a target for recovery after stroke or in depression." (PMID 40757562, 2025).